WIPI2 (WD repeat domain, phosphoinositide interacting 2)
Description:
Component of the autophagy machinery that controls the major intracellular degradation process by which cytoplasmic materials are packaged into autophagosomes and delivered to lysosomes for degradation. Involved in an early step of the formation of preautophagosomal structures. Binds and is activated by phosphatidylinositol 3-phosphate (PtdIns3P) forming on membranes of the endoplasmic reticulum upon activation of the upstream ULK1 and PI3 kinases. Mediates ER-isolation membranes contacts by interacting with the ULK1:RB1CC1 complex and PtdIns3P. Once activated, WIPI2 recruits at phagophore assembly sites the ATG12-ATG5-ATG16L1 complex that directly controls the elongation of the nascent autophagosomal membrane. [Isoform 4]: Recruits the ATG12-ATG5-ATG16L1 complex to omegasomes and preautophagosomal structures, resulting in ATG8 family proteins lipidation and starvation-induced autophagy. Isoform 4 is also required for autophagic clearance of pathogenic bacteria. Isoform 4 binds the membrane surrounding Salmonella and recruits the ATG12-5-16L1 complex, initiating LC3 conjugation, autophagosomal membrane formation, and engulfment of Salmonella.
Synonyms: WIPI-2; CGI-50; ATG21; FLJ12979; FLJ14217; FLJ42984; DKFZP434J154; DKFZp686P02188; ATG18B; IDDSSA
Tractability: Antibody: UniProt places it where antibodies can reach, with high confidence. PROTAC: ubiquitination databases record sites on it; its protein half-life has been measured.
Gene: Protein-coding gene on chromosome 7 (5,190,182 to 5,233,840, forward strand). Ensembl gene ENSG00000157954.
Subcellular location: Preautophagosomal structure membrane
Subcellular location (Human Protein Atlas): Cytosol; Nucleoplasm
Pathways (Reactome):
Autophagy: Macroautophagy
Gene Ontology:
Molecular function: phosphatidylinositol-3,5-bisphosphate binding; phosphatidylinositol-3-phosphate binding; protein binding; protein-macromolecule adaptor activity
Biological process: autophagosome assembly; autophagosome maturation; cellular response to starvation; protein localization to phagophore assembly site; autophagy of mitochondrion; glycophagy; nucleophagy; pexophagy; response to stress
Cellular component: autophagosome; autophagosome membrane; cytosol; membrane; phagophore assembly site; phagophore assembly site membrane; protein-containing complex
Genetic constraint (gnomAD): Loss-of-function variants: 28 observed, 49.83 expected, observed/expected ratio (o/e) 0.56, 90% interval 0.41 to 0.77. The upper end of that interval is the gene's LOEUF score, 0.77, which puts it in group 3 of 6, group 1 being the genes least tolerant of losing a copy. Missense variants: 484 observed, 567 expected, observed/expected ratio (o/e) 0.85, 90% interval 0.79 to 0.92. Synonymous variants: 254 observed, 231.11 expected, observed/expected ratio (o/e) 1.1, 90% interval 0.99 to 1.22.
Homologues: Orthologues: chimpanzee WIPI2 (99% identical), macaque WIPI2 (96% identical), chimpanzee WIPI2 (94% identical), rat Wipi2 (94% identical), guinea pig WIPI2 (93% identical), mouse Wipi2 (91% identical), pig WIPI2 (86% identical), tropical clawed frog wipi2 (83% identical), zebrafish wipi2 (83% identical), dog WIPI2 (77% identical), rabbit WIPI2 (72% identical). Paralogues in human: WIPI1 (55% identical), WDR45B (24% identical), WDR45 (22% identical).
Diseases named in the same sentence as WIPI2 in open-access papers:
WIPI2 is named in the same sentence as 32 diseases in open-access papers, as found by Europe PMC text mining. Sharing a sentence is not in itself a finding about the gene and the disease. The quoted sentences say what the papers report.
hepatocellular carcinoma (3 papers, 2023). A malignant tumor that arises from hepatocytes. "Regarding the pro-tumor effects of WIPI2, a recent research found that the expression of WIPI2 was higher in human hepatocellular carcinoma tissues and its high expression predicted a poor prognosis for HCC patients." (PMID 37207153, 2023). "For instance, WIPI2 regulates the proliferation of hepatocellular cancer cells through the AMPK signaling pathway." (PMID 36817452, 2023). "In a study of hepatocellular carcinoma (HCC) cells, the deletion of WIPI2 promoted apoptosis." (PMID 36769189, 2023).
Intellectual disability (3 papers, 2021 to 2026). "For instance, mutations in ATG5 are linked to congenital ataxia and developmental delay, while WIPI2 mutations result in global developmental delay and intellectual disability, demonstrating the diverse roles of autophagy proteins in neuronal health." (PMID 41277110, 2026). "Defects in WIPI2 cause a disease characterized mainly by intellectual disability and variable other features while pathogenic variants in WDR45B and WDR45 have been recently reported to cause El-Hattab-Alkuraya syndrome and beta-propeller protein-associated neurodegeneration (BPAN), respectively." (PMID 36157071, 2022). "In contrast, the proband of the second family carrying the p.(Arg242Trp) missense variant, similar to the initially reported WIPI2 cases, presented with a milder phenotype, encompassing moderate intellectual disability, speech and visual impairment, autistic features, and an ataxic gait." (PMID 34557665, 2021). "Defects in WIPI2, which plays an important role in autophagosome formation via ATG16L1 interaction and PtdIns3P expansion, cause a neurodevelopmental disorder characterized by global developmental delay/intellectual disability, reduced brain volume, and variable other features." (PMID 41277110, 2026).
colorectal cancer (2 papers, 2023). A primary or metastatic malignant neoplasm that affects the colon or rectum. "We preliminary searched in the FerrDb database found that WIPI2 may be a potential positive regulator of ferroptosis, so we wanted to further explore whether the effect of WIPI2 on colorectal cancer cell activity is associated with ferroptosis." (PMID 37207153, 2023). "CCK-8 results showed that depletion of WIPI2 (si-WIPI2) substantially inhibited the growth activity of colorectal cancer cells in the si-groups compared to the NC-group, and the inhibition rate was more significant in the 48h group compared to the 24h group." (PMID 37207153, 2023). "Gene expression profiling data showed that WIPI2 was significantly more expressed in colorectal cancer tissues than in normal tissues, and this result was affirmed by immunohistochemical section staining results." (PMID 37207153, 2023). "Our study suggested that WIPI2 had a promotional effect on the growth of colorectal cancer cells, and it also played an important role in the ferroptosis pathway." (PMID 37207153, 2023). "In conclusion, the expression intensity degree of WIPI2 was higher in most colorectal cancer tissues than in paracellular tissues." (PMID 37207153, 2023). "Next, we further investigated the sensitivity of WIPI2 to the ferroptosis inducer Erastin in colorectal cancer cells." (PMID 37207153, 2023). "To evaluate the expression level of WIPI2 in colorectal cancer tissues, we explored the expression of WIPI2 in CRC tissues and paracancerous tissues by immunohistochemical staining." (PMID 37207153, 2023). "Meanwhile, we also proved for the first time the relationship between WIPI2 expression and colorectal cancer cell growth." (PMID 37207153, 2023). "Our study is to focus on investigating the effect of WIPI2 on the growth and ferroptosis of colorectal cancer (CRC) cells and its potential mechanism." (PMID 37207153, 2023). "In this research, two si-RNAs targeting WIPI2, si#1 and si#3 were selected to inhibit the expression of WIPI2 in colorectal cancer cell lines to validate its regulatory role in colorectal cancer cells in vitro." (PMID 37207153, 2023). "Next, we used Erastin and transfected si-WIPI2 to detect cellular viability after combined treatment of colorectal cancer cells with CCK-8." (PMID 37207153, 2023). "We discovered that the expression of WIPI2 was greatly increased in human colorectal cancer tissues compared to paracancerous tissues." (PMID 37207153, 2023). "To further explore the importance of WIPI2 in colorectal cancer, we collected 41 normal tissues and 473 colorectal cancer tissues from TCGA." (PMID 37207153, 2023). "We analyzed the expression of WIPI2 in colorectal cancer versus normal tissues through The Cancer Genome Atlas (TCGA), and the relationship between clinical traits and WIPI2 expression and prognosis was assessed by univariate and multifactorial cox analysis." (PMID 37207153, 2023). "Public data from the TCGA platform showed that WIPI2 expression was significantly elevated in colorectal cancer tissues compared to paracancerous tissues, and high WIPI2 expressionpredicted poor prognosis for CRC patients." (PMID 37207153, 2023). "The results all suggest that WIPI2 may influence the ferroptosis pathway in the development of colorectal cancer by regulating the activity of ferroptosis proteins." (PMID 37207153, 2023). "Therefore, WIPI2 is most likely one of the important regulatory factors of Erastin-induced ferroptosis in human colorectal cancer cells." (PMID 37207153, 2023). "In vitro cellular assays also showed that when the expression of WIPI2 was knocked down, the growth and proliferation of colorectal cancer cells could be significantly inhibited." (PMID 37207153, 2023). "Therefore, we sought to investigate whether WIPI2 may influence the development of colorectal cancer via the ferroptosis pathway and aimed to explore its associated molecular mechanisms." (PMID 37207153, 2023).
colorectal cancer (continued). "After transient transfection of human colorectal cancer HCT116 cells with si-RNA, the protein expression level and fluorescence intensity of WIPI2 were reduced." (PMID 37207153, 2023). "We further investigated the expression levels of WIPI2 in tumor tissue and its paired paracancerous normal tissues in TCGA-CRC patients, and both results suggested that the expression of WIPI2 was higher in colorectal cancer tissues compared to normal tissue with notable differences (p<0.05)." (PMID 37207153, 2023).
cervical cancer (1 paper, 2025). A primary or metastatic malignant neoplasm involving the cervix. "However, the autophagy induced by RAB33A overexpression in cervical cancer cells was not inhibited by 3-methyladenine (3-MA), a PI3K inhibitor, and was independent of both Beclin1 (BECN1) and WD repeat domain, phosphoinositide interacting 2 (WIPI2)." (PMID 40000633, 2025).
colorectal adenocarcinoma (1 paper, 2023). The most common type of colorectal carcinoma. "However, WIPI2 still cannot be used as an independent prognostic factor for colorectal adenocarcinoma at this time." (PMID 37207153, 2023).
diffuse gastric adenocarcinoma (1 paper, 2021). An adenocarcinoma arising from the stomach. "Four DEGs including ATG10, ATG16L2, ULK4 and GABARAPL1 showed differences in diffuse gastric adenocarcinoma subgroup, while other four DEGs including ATG7 (probe 224025_s_at), GABARAPL1, WIPI2 and GABARAPL3 showed differences in gastric intestinal type adenocarcinoma subgroup." (PMID 33604190, 2021).
epilepsy (1 paper, 2024). A brain disorder characterized by episodes of abnormally increased neuronal discharge resulting in transient episodes of sensory or motor neurological dysfunction, or psychic dysfunction. "We found that SQSTM1 and VEGFA were significantly upregulated, while BNIP and WIPI2 were significantly downregulated in epilepsy model." (PMID 40217519, 2024). "The expression levels of SQSTM1 and VEGFA in epilepsy model samples were significantly higher than those in normal control, while BNIP and WIPI2 expression levels were notably decreased." (PMID 40217519, 2024).
Listeria infection (1 paper, 2019). "We were struck by the modification of four key regulators of autophagy by ISGylation, in particular the modification of mTOR and WIPI2 following infection in wild-type animals following Listeria infection and modification of AMBRA1 and RAB7 following infection in USP18C61A/C61A animals." (PMID 31772204, 2019).
lymphoma (1 paper, 2023). A malignant (clonal) proliferation of B- lymphocytes or T- lymphocytes which involves the lymph nodes, bone marrow and/or extranodal sites.
Stroke (1 paper, 2021). Sudden impairment of blood flow to a part of the brain due to occlusion or rupture of an artery to the brain. "Specifically, when comparing MCAO vs. sham, proteins FBXO7, WIPI2, NTRK2, A0A0G2JY03, and ITGB8 appeared clearly underexpressed, whereas MAP1a and CPQ were overexpressed, indicating a clear effect of the stroke (MCAO injury) on the individuals." (PMID 35008673, 2021).
cancer (7 papers, 2020 to 2025). A tumor composed of atypical neoplastic, often pleomorphic cells that invade other tissues. "Collectively, these results suggest that HUWE1 normally serves to suppress autophagy by ubiquitinating and triggering degradation of ATG101 and WIPI2, which in turn represses the survival of cancer cells." (PMID 34502089, 2021). "WIPI2, ATG9B, MAP1LC3A, and RB1CC1 have higher frequencies of gain mutation frequencies in the pan-cancer analysis." (PMID 34636718, 2021). "Further, double knockdown of both ATG101 and WIPI2 in shHUWE1 cancer cells significantly increased the apoptotic death rate compared to that in shCTL cells." (PMID 34502089, 2021). "As a connection between PI3K complex, ULK complex and ATG12 system, WIPI2 showed higher expression in cancer tissue." (PMID 33604190, 2021). "WIPI2 overexpression significantly inhibited cancer cell colony formation, but ANXA6 knockdown weakened the suppressive effect of autophagy induction." (PMID 33135350, 2020). "Consistently, PI4KB-Peptide-1 mediated inhibition of PI4KB phosphorylation on S256 and T263, and therefore hindered RINCAA, including LC3 lipidation, autophagic flux determined by mitophagy, and WIPI2 puncta formation, across various RAS-mutated cancer cell lines." (PMID 40055523, 2025). "Therefore, our study is dedicated to research the potential cancer-promoting mechanisms of WIPI2 in CRC, with a view to filling some of the gaps in WIPI2 research and bringing new strategies and ideas to the diagnosis and treatment of CRC." (PMID 37207153, 2023). "Accordingly, we examined whether increased autophagy in HUWE1-depleted cancer cells could be suppressed by knockdown of WIPI2 as well as by ATG101 knockdown." (PMID 34502089, 2021). "WIPI2, COL4A2, HDAC4, CUGBP2, PTPRN2 and RUNX2 are Top 6 differential methylation genes, and all of them were reported to take part in regulation of cancers." (PMID 36817452, 2023). "Three genes, WIPI2, ATG16L1, and GABARAPL1, showed comparable changes in various cancers." (PMID 34636718, 2021).
infection (4 papers, 2014 to 2022). The state of being infected such as from the introduction of a foreign agent such as serum, vaccine, antigenic substance or organism. "We showed that several autophagy-related proteins (LC3, ATG16L1, and WIPI2) are recruited to C. albicans invasion sites during infection of epithelial cells, including intestinal epithelial cells (cell line and gut explants)." (PMID 35086419, 2022). "After infection with Salmonella, WIPI2 on p62-positive SCVs colocalized with LC3, LAMP1, and ubiquitin." (PMID 24954904, 2014). "Finally, we demonstrate that animals and cells with enhanced ISGylation have increased basal and infection-induced autophagy through the modification of mTOR, WIPI2, AMBRA1, and RAB7." (PMID 31772204, 2019). "The consequences of modification sites on WIPI2 and AMBRA1 are more difficult to predict given less is known with regard to their structural features, so we assessed general autophagy levels following infection." (PMID 31772204, 2019).
tumor (3 papers, 2021 to 2024). "In recent years, it has been showed that WIPI2 may be strongly associated with tumor development." (PMID 37207153, 2023). "Next, the association between the expression level of WIPI2 and prognosis-related clinicopathological characteristics, such as whether patients had distant metastases (M), whether they had regional lymph node metastases (N), clinical stage and depth of tumor infiltration (T), was further verified." (PMID 37207153, 2023). "IHC results showed that WIPI2 was weakly positive expressed in the cytoplasm in paracancerous colorectal tissues and moderately to strongly positive expressed in the cytoplasm of tumor cells in tumor tissues." (PMID 37207153, 2023). "Furthermore, we found that the expression of WIPI2 correlated with the degree of tumor differentiation and age of patients by sorting out the pathological information collected from colorectal patients, which also indicates that WIPI2 is indeed a gene associated with multiple pathological features." (PMID 37207153, 2023). "Thus, either the HUWE1/ATG101 or HUWE1/WIPI2 pathway could be potential targets for suppressing tumor cell survival, and these reverse combinational approaches may be more effective." (PMID 34502089, 2021). "Furthermore, as shown in our analysis of the GO pathway enriched for high and low levels of WIPI2 respectively, WIPI2 was also significantly associated with the regulation of stem cell diversity, suggesting that WIPI2 may also exert its regulatory role by regulating the stemness of tumor cells." (PMID 37207153, 2023). "Furthermore, the pro-tumor effect of WIPI2 and its correlation with ferroptosis suggest that there may be other more dominant mechanisms, such as autophagy, for the regulatory role of WIPI2 on tumor cells." (PMID 37207153, 2023).
neurodegenerative disease (2 papers, 2022 to 2024). A disorder of the central nervous system characterized by gradual and progressive loss of neural tissue and neurologic function. "This included two known proteins associated with MERCS, MFN2 and TOMM40, as well as neurodegenerative disease-associated genes such as WIPI2, CLASRP, BAG6, SOD1 and FUS which increase MERCS and MTCH2 and PARL which decrease MERCS." (PMID 38467609, 2024). "Three proteins, WIPI2, WDR45B, WDR45, are already associated with Mendelian neurodegenerative diseases." (PMID 36157071, 2022).
neurodevelopmental disorder (2 papers, 2021 to 2023). A behavioral and cognitive disorder with onset during the developmental period that involves impaired or aberrant development of intellectual, motor, or social functions. "Here, we report four individuals from two consanguineous families harbouring two ultra-rare homozygous WIPI2 missense variants and presenting with a neurodevelopmental disorder." (PMID 34557665, 2021). "The homozygous WIPI2 variant c.745G>A; p.(Val249Met) (NM_015610.4) has recently been associated with a neurodevelopmental disorder in a single family." (PMID 34557665, 2021). "Collectively, our findings provide evidence that biallelic WIPI2 variants cause a neurodevelopmental disorder of variable severity and disease course." (PMID 34557665, 2021). "Mutations in WDR45B, which encodes WIPI3, also cause a complex neurodevelopmental disorder called El-Hattab-Alkuraya syndrome (OMIM#617977), while mutations in WIPI2 cause a neurodevelopmental disorder accompanied by skeletal and cardiac abnormalities (OMIM#618453)." (PMID 37364041, 2023).
bacterial infection (1 paper, 2014). "We asked if WIPI2 interaction with ATG16L1 was also required for the recruitment of the LC3 to the phagophore during bacterial infection." (PMID 24954904, 2014).
WIPI2 also shares sentences with these, for which no sentence is quoted: adenocarcinoma (1 paper); Baraitser-Winter syndrome 1 (1); cerebellar ataxia (1); COVID-19 (1); developmental delay (1); El-Hattab-Alkuraya syndrome (1); gastric intestinal type adenocarcinoma (1); hypogonadotropic hypogonadism (1); leukodystrophy (1); melanoma (1); Mental retardation, autosomal dominant 48 (1); Nystagmus (1); osteogenesis imperfecta (1); pancreatic cancer (1); Parkinson disease (1); pulmonary TB (1).